FIG4 (FIG4 phosphoinositide 5-phosphatase)
Diseases named in the same sentence as FIG4 in open-access papers (continued):
Sharing a sentence is not in itself a finding about the gene and the disease.
COVID-19 (2 papers, 2023 to 2025). A disease caused by infection with severe acute respiratory syndrome coronavirus 2. "In the case of the resistance towards COVID-19, the most significant SNP (rs7772946) was located on chromosome 6, in the intron of FIG4." (PMID 36662838, 2023). "By 6 weeks post-inclusion, COVID-19 hypermethylation of genes with the highest fold-change compared to healthy controls included FAM178B, FYN, TMCC1, TMEM212-AS1, and FIG4, while the top five hypomethylated genes were GIT2, PDGFRB, SEMA6D, TNFAIP8, and ETV6." (PMID 41227320, 2025). "None of identified significant SNPs (in the intron of AJAP1 and the intron of FIG4) and none of the missense variants with a potential causal function on a severe outcome of COVID-19 (in the exon of PM20D1 and the exon of LRP4), found in our study, have been previously associated with COVID-19." (PMID 36662838, 2023).
Alzheimer disease (1 paper, 2016). A progressive, neurodegenerative disease characterized by loss of function and death of nerve cells in several areas of the brain leading to loss of cognitive function such as memory and language. "Here we show that the Amyloid Precursor Protein (APP), a central molecule in Alzheimer’s disease, associates with the PIKfyve complex (consisting of Vac14, PIKfyve and Fig4) and that the APP intracellular domain directly binds purified Vac14." (PMID 26216398, 2016).
distal motor neuropathy (1 paper, 2017). "A 17-year-old man with distal motor neuropathy and optic atrophy (CMT type 6) carried a single previously reported heterozygous c.2386C>T, p.(Gln796*) mutation in FIG4." (PMID 28251916, 2017).
Intellectual disability (1 paper, 2021). "Also, other genes encoding proteins of the inositol phosphatase metabolism (e.g., INPP5K, FIG4, INPP5E) are associated with autosomal recessive syndromes of intellectual disability." (PMID 33168985, 2021).
leukodystrophy (1 paper, 2025). Leukodystrophies are a group of rare, progressive, metabolic, genetic diseases that affect the brain, spinal cord and often the peripheral nerves. "A C‐terminal truncation, Fig4‐ΔCt113, which corresponds to a human Fig4 variant associated with leukodystrophy that is missing the last 115 amino acids as the result of a splice junction mutation, also conferred rapamycin tolerance." (PMID 40741910, 2025). "Fig4 point mutants conferring rapamycin tolerance included Fig4‐I59T (CMT4J, ALS, and PLS), Fig4‐E72Y (ALS), and Fig4‐Y181S (leukodystrophy)." (PMID 40741910, 2025).
mitochondrial neurogastrointestinal encephalomyopathy (1 paper, 2021). A syndrome characterized by the association of gastrointestinal dysmotility, peripheral neuropathy, chronic progressive external ophthalmoplegia and leukoencephalopathy. "Other potential CIDP mimics reported include CMT4J (FIG4 mutation), CMTX (Cx32 mutation), mitochondrial neurogastrointestinal encephalomyopathy (MNGIE), and additional diagnoses, but in general those have a different presentation and can usually be clinically differentiated from CIDP." (PMID 33639867, 2021).
osteopetrosis (1 paper, 2023). Osteopetrosis, also known as marble bone disease, is a descriptive term that refers to a group of rare, heritable disorders of the skeleton characterized by increased bone density on radiographs. "The G215R allele of CLCN7, used here to reduce CLCN7 function in the mouse, was originally identified in a patient with dominant osteopetrosis which results from impaired osteoclast-mediated bone resorption and is thus physiologically quite different from the deposition defect in FIG4 mutants." (PMID 37363915, 2023).
prion disease (1 paper, 2021). A transmissible disease that is caused by a protein that is able to induce abnormal folding of normal cellular proteins, leading to characteristic spongiform brain changes, which are associated with neuronal loss without an inflammatory response. "While VAC14 and FIG4 levels were not affected at any time point during the progression of prion disease, co‐immunoprecipitation experiments revealed that VAC14 lost its association with FIG4 and PIKfyve in prion‐infected brains at the terminal stage of the disease." (PMID 34291577, 2021).
Sensory neuropathy (1 paper, 2020). Peripheral neuropathy affecting the sensory nerves. "Although FIG4 is classified as a major ALS gene, it was originally reported as a causative gene for CMT4J, an AR motor and sensory neuropathy." (PMID 32397312, 2020).
spinocerebellar ataxia type 6 (1 paper, 2023). Spinocerebellar ataxia type 6 (SCA6) is the most common subtype of autosomal dominant cerebellar ataxia type III (ADCA type III) characterized by late-onset and slowly progressive gait ataxia and other cerebellar signs such as impaired muscle coordination and nystagmus. "Furthermore, the CACNA1A gene and the FIG4 gene are both implicated as causal for progressive neurodegenerative skeletal muscular diseases in humans, and spinocerebellar ataxia type 6 and Charcot-Marie-Tooth Neuropathy Type 4J, respectively." (PMID 37510383, 2023).
viral infection (1 paper, 2023). "Next, to confirm whether IFNβ overproduction during viral infection is a common phenomenon in all ALS patients, we examined IFNβ production by cells from several ALS patients with mutations in the ALS-causative genes, SOD1, FUS, ANG, FIG4, and TARDBP." (PMID 37352136, 2023).
neurological disease (8 papers, 2022 to 2025). "Later on, other neurological diseases such as Yunis-Varón syndrome, familial epilepsy, and cerebral hypomyelination were also linked to Fig4 mutations." (PMID 36493904, 2022). "The lipid phosphatase Fig4 is conserved in all eukaryotes and is associated with human neurological diseases for which there are currently no specific therapies." (PMID 40741910, 2025).
peripheral neuropathy (8 papers, 2011 to 2025). A disorder affecting the peripheral nervous system. "Our investigations have been conducted on fibroblasts, but it is the functional effects of LITAF and FIG4 mutations in Schwann cells that are likely to help explain the underlying pathomechanism of these inherited demyelinating peripheral neuropathies." (PMID 33059769, 2020). "Loss of Fig4 function in the plt (pale tremor) mouse produces spongiform degeneration of the brain and peripheral neuropathy." (PMID 22028665, 2011). "Loss of Fig4 in the mouse causes the plt (pale tremor) phenotype, characterized by extensive neuronal vacuolization and degeneration and by a peripheral neuropathy." (PMID 22028665, 2011). "Loss of Fig4 in mouse provokes the plt phenotype characterized by massive neurodegeneration and peripheral neuropathy." (PMID 22028665, 2011). "Complete or strong loss of FIG4 (encoding polyphosphoinositide phosphatase) causes a lethal multisystem disorder Yunis–Varon syndrome with severe bone and neurologic features, whereas partial loss of FIG4 causes a peripheral neuropathy: Charcot-Marie-Tooth Type 4J." (PMID 37556311, 2023).
neurodegenerative disease (5 papers, 2011 to 2025). A disorder of the central nervous system characterized by gradual and progressive loss of neural tissue and neurologic function. "Comparable accumulation of enlarged lysosomes causing the rapid development of severe brain degeneration was observed in both constitutive and neuron-specific Fig4 knock-out murine models, while in Drosophila Fig4 loss correlated with motility impairments and shorter lifespan." (PMID 35708843, 2022). "This mechanistic framework may explain the paradoxical therapeutic effects of acute PIKfyve inhibition in neurodegenerative disease models, despite the pathological consequences of genetic PIKfyve/Fig4/Vac14 dysfunction." (PMID 41315403, 2025). "In another example of the importance of interactions between proteins in this complex, the missense mutation of Vac14 in the ingls mouse which reduces the affinity of VAC14 for FAB1 and results in a neurodegenerative disease that closely resembles the Fig4 null mice." (PMID 21655088, 2011).
neurodevelopmental disorder (1 paper, 2021). A behavioral and cognitive disorder with onset during the developmental period that involves impaired or aberrant development of intellectual, motor, or social functions. "The pathomechanism explaining the disease mechanism remains unknown, however several others genes of the inositol phosphatase metabolism (e.g., INPP5K, FIG4, INPP5E, ITPR1) are correlated with phenotypes of neurodevelopmental disorders." (PMID 33168985, 2021).
neuromuscular disease (1 paper, 2017). "Mutations in the human FIG4 gene cause Charcot-Marie-Tooth type 4J disease, a recessive neuromuscular disease characterized by neuron demyelination." (PMID 28294977, 2017). "With MTM1, MTMR2, MTMR5 and MTMR13, FIG4 is thus the fifth gene encoding a lipid phosphatase involved in a neuromuscular disease." (PMID 28294977, 2017).
FIG4 also shares sentences with these, for which no sentence is quoted: dementia (3 papers); myopathies (2); poly)neuropathy (2); amyotrophic lateral sclerosis type 11 (1); Arrhythmogenic right ventricular dysplasia (1); Brown-Vialetto-Van-Laere syndrome (1); cancer (1); Charcot-Marie-Tooth disease type 4 (1); Charcot-Marie-Tooth disease type 4B (1); cognitive decline (1); demyelinating (1); Dystonia (1); epilepsy (1); Fabry disease (1); frontotemporal dementia (1); hereditary motor and sensory neuropathy (1); hypophosphatasia (1); inflammatory bowel disease (1); invasive breast carcinoma (1); mandibuloacral dysplasia (1); multiple myeloma (1); multiple system atrophy (1); optic atrophy (1); pale (1); Polycystic kidney dysplasia (1); prostate adenocarcinoma (1); pycnodysostosis (1); sarcoma (1); sensorimotor peripheral neuropathy (1); synucleinopathy (1).
A further 3 diseases each share a sentence with FIG4 in 1 paper.